MCM3 (minichromosome maintenance complex component 3)
Diseases named in the same sentence as MCM3 in open-access papers (continued):
Sharing a sentence is not in itself a finding about the gene and the disease.
tumor (continued). "Bcl2, VEGFA, PTEN, Jun, Fos, APC2 were up-regulated and Ccna2, Cdc25a, Mcm3, Mcm6, Ccnb2, Mcm5, Cdk1, Gadd45a, Myc were down-regulated in MMQ tumor stem-like cells group." (PMID 28163656, 2017). "Expression of MCM3, which is upregulated in LIHC tumours compared to adjacent normal tissues, is suppressed specifically by effective compounds in LIHC." (PMID 28699633, 2017). "In the pathway in cell cycle, we found that the expression of Ccna2, Cdc25a, Mcm3, Mcm6, Ccnb2, Mcm5, Cdk1, Gadd45a were down-regulated in the MMQ tumor stem-like cells." (PMID 28163656, 2017). "In pathway in cancer and cell cycle, Bcl2, VEGFA, PTEN, Jun, Fos, APC2 were up-regulated and Ccna2, Cdc25a, Mcm3, Mcm6, Ccnb2, Mcm5, Cdk1, Gadd45a, Myc were down-regulated in the MMQ tumor stem-like cells." (PMID 28163656, 2017). "Consequently, MCM2 and MCM3 may help to predict tumor behavior." (PMID 26823641, 2015). "Applying these MCM family expression cutoff to Kaplan-Meier survival curve estimation revealed decreased survival probability for patients with tumor expressing high levels of MCM2, MCM3 and MCM7 (p < 0.05)." (PMID 25046975, 2014). "In addition, tumor weight showed similar changes; the tumor weight increased after ZMIZ2 overexpression, but remarkably decreased after MCM3 knockdown." (PMID 41502508, 2025). "Among 232 Chinese GC patients, validation through immunohistochemical methods showed that the protein levels of CDC6 and MCM3 in tumor and nontumor tissues had significantly different histochemistry scores (H-scores)." (PMID 35537781, 2022). "Finally, two tumor suppressors, CDKN2B and TSLC1, were upregulated upon MCM3 knockdown in TamR cells." (PMID 33398005, 2021). "The increase in MCM2, MCM3, and MCM6 is related to poor performance of the tumor." (PMID 33234725, 2020). "The tumor growth (volume and weight) was dramatically inhibited in the sh-MCM3 group unlike in the control group." (PMID 32597491, 2020). "Transcription of specific genes like MCM3 and CDKN1B effects tumor suppressor ability of BAP1." (PMID 26680512, 2015). "We reviewed each grade of tumor separately and investigated whether the expression of MCM2, MCM3 and MCM7 predicts patient survival within each subgroup." (PMID 25046975, 2014). "We found a significant increase in MCM2 (3.5 fold), MCM3 (3.1 fold), MCM4 (4.3 fold), MCM5 (3.8 fold), MCM6 (3.5 fold), MCM7 (3.0 fold) and MCM10 (3.6 fold) expressions in tumor tissues (the average fold value of three grades) compared to the normal brain controls." (PMID 25046975, 2014). "MCM3 do not show significant change in the expression levels of tumor (0.603±0.388, median = 0.61, p = 0.069) and cell lines (0.705±0.398, median = 0.75, p = 0.089) compared to normal (0.49±0.39, median = 0.5)." (PMID 23874974, 2013). "Compared to non-tumor cells, MCM3 was significantly overexpressed in tumor cells." (PMID 36133906, 2022). "The TN clusters (TN and TN+Her2) include proliferative proteins (MCM3 and 5), translation related proteins (RCL1, MRPS27, EIF2S2 and EEF1G) and metabolic enzymes (glutaminase and hexokinase 2), which reflect the higher dependence on glutamine and glucose of TN versus the other tumours." (PMID 26725330, 2016). "In contrast, nonproliferating tumor cells subjected to enough stimuli to initiate new proliferation would present an immunoexpression pattern negative for Ki-67 and positive for MCM2 and MCM3." (PMID 26823641, 2015). "Although there are no available AM studies with MCM2 and MCM3, predicting tumor behavior could be supported by statistical significance between the expression of MCM2 and MCM3 versus Ki-67 in histological subtypes." (PMID 26823641, 2015).
cancer (57 papers, 2006 to 2026). A tumor composed of atypical neoplastic, often pleomorphic cells that invade other tissues. "Since MCM3 is associated with various cancer types, this suggests the vital role this protein plays in DNA replication and cell proliferation, which underlies the very development and progression of cancer." (PMID 39941813, 2025). "By using the GEPIA database, we analysed the association between MCM3 and clinical stage across cancers." (PMID 38698811, 2024). "The results showed that MCM3 expression levels were closely linked to different outcomes in many cancers." (PMID 38698811, 2024). "We found that MCM3 expression was significantly associated with the clinical stages of eight cancers, including ACC, BRCA, CESC, KIRC, LIHC, OV, SKCM and TGCT." (PMID 38698811, 2024). "These genes, including Smc2, Mcm3, Ccnd1, Rasal2, Mcm6, and Mad2l1, are linked to cancer progression and metabolic regulation." (PMID 39272991, 2024). "In our study, a pan-cancer analysis and a single-cell analysis were performed to explore the prognostic role, immunological value, and associated biological mechanisms of MCM3." (PMID 38698811, 2024). "MCM3, which is a component of the hexameric protein complex, has diagnostic and prognostic value in some cancers." (PMID 38698811, 2024). "In our research, single-cell analysis demonstrated that MCM3 was associated with the cell cycle, DNA damage and DNA repair across cancers." (PMID 38698811, 2024). "Single-cell data from CancerSEA were analysed to assess the biological functions associated with MCM3 in 14 cancers." (PMID 38698811, 2024). "Overall, investigations of MCM3 have been largely limited to a small number of cancer types, and the role of MCM3 in various malignancies and the underlying mechanisms remain incompletely understood." (PMID 38698811, 2024). "Since snuff is considered a risk factor for the progression of cancer, it was investigated along with MCM3 expression to observe any association between the two variables." (PMID 36611359, 2022). "Overexpression of the mini-chromosome maintenance 3 (MCM3) gene has been reported in colon and other cancers, and has been implicated in a number of forms of carcinogenesis in humans in maintaining cancer cell growth." (PMID 31263147, 2019). "Considering that TMB, MSI, and neoantigen expression are common genomic alterations that are closely associated with cancer prognosis and immunotherapeutic responses, we measured the association between MCM3 and these alterations across cancers." (PMID 38698811, 2024). "As the heatmap shows, MCM3 is closely linked to these biological functions in most cancers." (PMID 38698811, 2024). "MCM2-7 were all upregulated in carcinoma tissue in our data, and MCM3, MCM4, and MCM6 were associated with differential miRNA expression, including hsa-miR-106b-5p, hsa-miR-17-5p, hsa-miR-19b-3p, hsa-miR-20a-5p, hsa-miR-20b-5p, hsa-miR-25-3p, and hsa-miR-93-5p." (PMID 29725503, 2018). "A reduction in the level of some MCM proteins in human cancer cells (MCM5 in U20S cells or MCM3 in Hela cells) causes a rapid increase in the level of DNA damage under normal conditions of cell proliferation and a loss of viability when the cells are subjected to replication interference." (PMID 22102875, 2011). "Finally, we found that reduced MCM3 levels could rescue the cancer susceptibility of two different Chaos3 models." (PMID 20838603, 2010). "We then systematically evaluated the associations of MCM3 with immune signatures, mismatching repair (MMR) genes, RNA modulator genes, cancer stemness, programmed cell death (PCD) genes, the TMB, MSI, and neoantigen levels." (PMID 38698811, 2024). "The expression of MCM3 was strongly associated with the expression of immune checkpoint molecules and the TMB in most cancers." (PMID 38698811, 2024). "The aim of our study was to explore the expression, prognostic role, and immunological characteristics of MCM3 across cancers." (PMID 38698811, 2024).
cancer (continued). "The MCM3 expression results and prognostic value in most cancers were mainly determined based on publicly available data and need to be validated in clinical cohorts." (PMID 38698811, 2024). "GO and KEGG results indicated that MCM3 was mainly involved in cell cycle-related processes and cancer-related pathways." (PMID 38698811, 2024). "We found that in most cancers, MCM3 was closely related to the immune score, stromal score, and ESTIMATE score." (PMID 38698811, 2024). "In our further study, MCM3 was found to be highly expressed in cancer tissues and KYSE30 and TE-1 cell lines and its expression was decreased in cell lines transfected by sh-circ0032746." (PMID 38200573, 2024). "Among these genes, MCM3 was significantly correlated with most pyroptosis genes across cancers, except for CHOL, MESO and UCS." (PMID 38698811, 2024). "We further explored the genomic alteration status of MCM3 across cancers via the cBioPortal website." (PMID 38698811, 2024). "Although we focused on RBM15 and serine metabolism in this study, network analysis revealed that the relationship between RBM15 and other genes with oncogenic potential (CDC42, CDC14B, STK40, BRD3, CPNE1, and MCM3) is also crucial for cancer cell survival." (PMID 38825643, 2024). "This heatmap, based on a dataset including samples from NILM, ASC-US, and ≥LSIL groups, displays two main clusters: cancer markers (MCM3, CEACAM5, S100P, ICAM1) on the left and healthy markers (CRNN, EVPL, DSC2) on the right side of the figure." (PMID 37445651, 2023). "The GEPIA 2 database also revealed higher MCM3 mRNA expression levels in cancer tissues compared to those in normal tissues in the Oncomine database." (PMID 36133906, 2022). "The gene effect analysis of the DepMap database also indicated the dependence of cancer cells on MCM3." (PMID 36133906, 2022). "MCM3 overexpression is an oncogenic event in many types of cancers, including EC, and is correlated with the expression of Ki-67 and estrogen and progesterone receptors." (PMID 34859821, 2021). "We used the ONCOMINE database to compare the expression levels of MCM3 mRNA across cancers and its mRNA expression with that in corresponding normal tissues." (PMID 34671420, 2021). "MCM3 has been found to overexpress in various of cancers, and the specific high-expression in cancerous cells rendered it an ideal biomarker for detecting malignant cells." (PMID 33936158, 2021). "Again, genes such as GADD45B (growth arrest and DNA-damage-inducible, beta), HDAC1 (histone deacetylase 1), and MCM3 (minichromosome maintenance complex component 3) were oppositely coordinated in the cancer nodule in contrast to the normal tissue." (PMID 33302383, 2020). "Up to this point, it is interesting to note that in both cell lines, MP-HX downregulated all six top-ranked genes (PLK1, MCM2, MCM3, MCM7, MCM10 and SKP2) that were proposed to be cancer-associated (Wu, Zhu & Zhang, 2012)." (PMID 30042885, 2018). "It is interesting to note that all six top-ranked genes proposed to be cancer-associated (PLK1, MCM2, MCM3, MCM7, MCM10 and SKP2) were downregulated by MP-HX in both cell lines." (PMID 30042885, 2018). "MCM3 is a novel proliferation marker and is useful to determine the clinical behavior and prognosis in several cancers." (PMID 30363964, 2018). "Conversely, MCM3 (associated with poor prognosis) was found to be significantly upregulated in the PD cancer-stromal doublets over their cancer and stromal singlet counterparts, but not in the CR and PR groups." (PMID 40280979, 2025). "Cancers rely on the activation of DNA repair pathways to maintain genomic stability, stemness, and chemotherapy resistance; therefore, further evaluation of the relationship of MCM3 with DNA repair genes and cancer stemness across cancers is warranted." (PMID 38698811, 2024). "Herein, we comprehensively assessed the expression and prognostic role of MCM3 across cancers." (PMID 38698811, 2024).
cancer (continued). "However, the effect of MCM3 on the immune microenvironment of these cancers and its prognostic value require further study." (PMID 38698811, 2024). "Overall, genetic variations in MCM3 occur in less than 5% of most cancers." (PMID 38698811, 2024). "Interestingly, we also found that MCM3 was positively correlated with most RNA modulator genes across cancers." (PMID 38698811, 2024). "Taken together, these results suggest that MCM3 could be not only an immunotherapy target but also a cell cycle checkpoint, thus indicating that MCM3 may be a promising therapeutic target in cancer." (PMID 38698811, 2024). "One member of this family, MCM3, is reportedly active in most cancers." (PMID 36133906, 2022). "Previous studies have shown overexpression of MCM3 in many cancers." (PMID 34671420, 2021). "KEAP1, MCM3, and NRF2 interactions seem to be part of some complex regulatory mechanisms, and those interactions could be exploited in cancer therapy and perhaps against altered MCM3 to inhibit NRF2 function or DNA replication process by this protein in cancers." (PMID 39941813, 2025). "Moreover, we observed a positive correlation between MCM3 expression and DMPsi in DLBC, LGG and STAD and a negative correlation between MCM3 expression and THYM, KIRP and THCA, thus suggesting that MCM3 may be involved in DNA repair-mediated cancer stemness." (PMID 38698811, 2024). "mRNA expression analysis revealed that FOXM1 and MCM3 were upregulated, whereas SH3BP5 and PAPSS2 were downregulated in cancer tissues compared with normal tissues." (PMID 41750695, 2026). "Remarkably, the group of cancer-related proteins,i.e., CEACAM1,CEACAM5, and CEACAM6 as well as the minichromosome maintenance complexcomponents MCM3, MCM4, and MCM6 showed clear protein abundance patternsrelated to the radiation response." (PMID 40574313, 2025). "However, the mechanism of MCM3 function in most cancers is still unknown." (PMID 38698811, 2024). "MCM3, which is involved in these functions, belongs to the minichromosome maintenance (MCM) family and has been previously reported in relation to cancer." (PMID 38066476, 2023). "We observe that the mini-chromosome maintenance proteins (MCMs) MCM2, MCM3, MCM6 and MCM7, which were upregulated in most of the cancers, also regulate the expression of a significant number of high centrality genes in the network." (PMID 34728699, 2021). "We further searched genes closely related to MCM3 through the GEPIA database, UALCAN cancer database, and LinkedOmics." (PMID 34671420, 2021). "We detected the expression of the other six genes (MCM3, SPATS2, RRM2, NT5DC2, LRRC1, and RNASEH2A) in 30 pairs of HCC and para-carcinoma tissue by immunohistochemical staining assays." (PMID 32213663, 2020). "We selected the overlapped genes-PLK1, MCM2, MCM3, MCM7, MCM10 (ranked 13 by NGP-NR in NSCLC patient datasets) and SKP2 to investigate their functions in cancer." (PMID 22838965, 2012). "This modification might influence MCM3 function or its interactions within the MCM2-7 complex and, consequently, influence DNA replication in cancer cells." (PMID 39941813, 2025). "For the MMR signatures, we found a significant positive correlation between them and MCM3 broadly in pan-cancer, and a negative correlation between EPCAM and MCM3 expression in LGG and THYM." (PMID 38698811, 2024). "MCM3 and TMB were positively correlated in 12 cancers and negatively correlated in three cancers." (PMID 38698811, 2024). "MCM3 and INPP4B has been reported before to be related to cancer, while other three might be potential candidates for further study." (PMID 35842613, 2022). "MCM3, a member of the MCM family of DNA-dependent ATPases that bind to replication origins and support a single round of DNA replication, has demonstrated dysfunction in most cancers." (PMID 36133906, 2022).
cancer (continued). "The molecular basis for these phenotypes does not appear to be directly related to GIN, because whereas Mcm3 hemizygosity rescued several phenotypes, and delayed cancer latency in Mcm4Chaos3/Chaos3 mice, it did not concommitantly decrease MN." (PMID 20838603, 2010). "Overall, MCM3 expression was positively related to TMB in 12 cancers, especially ACC, DLBC, LGG, PAAD and STAD, thus suggesting that patients with high MCM3 expression in these cancers may be more sensitive to immunotherapy." (PMID 38698811, 2024). "Furthermore, Minichromosome maintenance complex component 3 (MCM3), the third hub, is included in the cell cycle pathway (hsa04110), which is important to the cancer research because alterations in the mechanism characterize the abnormal proliferation of human malignant tumors." (PMID 26138921, 2015). "The top-ranked genes by NGP-PLK1, MCM2, MCM3, MCM7, MCM10 and SKP2 might coordinate to promote cell cycle related processes in cancer but not normal cells." (PMID 22838965, 2012). "Our results suggest that the top-ranked genes by NGP-PLK1, MCM2, MCM3, MCM7, MCM10 and SKP2 might coordinate to promote cell cycle related processes in cancer but not normal cells." (PMID 22838965, 2012).
MCM3 also shares sentences with these, for which no sentence is quoted: astrocytoma (3 papers); larynx (3); salivary gland tumors (3); thyroid cancer (3); colon adenocarcinoma (2); esophageal squamous cell carcinoma (2); head and neck squamous cell carcinoma (2); lung squamous cell carcinoma (2); malignant glioma (2); malignant salivary gland tumours (2); non-small cell lung carcinoma (2); pancreatic cancer (2); papillary thyroid carcinoma (2); acute myeloid leukemia (1); adenocarcinoma (1); ameloblastic carcinoma (1); anaplastic astrocytoma (1); benign prostatic hyperplasia (1); benign tumor (1); bladder urothelial carcinoma (1); brain cancer (1); cholangiocarcinoma (1); Cirrhosis (1); Cornelia de Lange syndrome (1); cutaneous T-cell lymphomas (1); endometrial endometrioid adenocarcinoma (1); endometrial mixed adenocarcinoma (1); endometrial serous adenocarcinoma (1); epilepsy (1); erythroplakia (1).
A further 20 diseases each share a sentence with MCM3 in 1 paper.